CST8 (cystatin 8)
Description:
Performs a specialized role during sperm development and maturation.
Synonyms: CRES; CTES5
Tractability: Antibody: UniProt places it where antibodies can reach, with medium confidence; UniProt predicts a signal peptide or a membrane-spanning region; its Gene Ontology location is reachable by antibodies, with medium confidence.
Gene: Protein-coding gene on chromosome 20 (23,491,101 to 23,496,010, forward strand). Ensembl gene ENSG00000125815.
Subcellular location: Secreted
Gene Ontology:
Molecular function: cysteine-type endopeptidase inhibitor activity
Cellular component: cell surface; cytoplasm; extracellular region
Genetic constraint (gnomAD): Loss-of-function variants: 14 observed, 8.31 expected, observed/expected ratio (o/e) 1.68, 90% interval 1.05 to 1.95. That is too few expected variants to judge how well the gene tolerates losing a copy. Missense variants: 141 observed, 122.81 expected, observed/expected ratio (o/e) 1.15, 90% interval 1 to 1.32. Synonymous variants: 55 observed, 44.5 expected, observed/expected ratio (o/e) 1.24, 90% interval 0.99 to 1.55.
Homologues: Orthologues: chimpanzee CST8 (99% identical), macaque CST8 (77% identical), rabbit CST8 (65% identical), dog CST8 (60% identical), mouse Cst8 (58% identical), guinea pig CST8 (57% identical), rat Cst8 (56% identical), zebrafish si:busm1-57f23.1 (23% identical), Caenorhabditis elegans cpi-2 (16% identical), Caenorhabditis elegans cpi-1 (15% identical), Caenorhabditis elegans K08B4.7 (8% identical). Paralogues in human: CST11 (32% identical), CST3 (32% identical), CST4 (28% identical), CST1 (27% identical), CSTL1 (27% identical), CST2 (27% identical), CST5 (25% identical), CST6 (25% identical), CST7 (23% identical), CST9L (20% identical), CST9 (15% identical).
Diseases named in the same sentence as CST8 in open-access papers:
CST8 is named in the same sentence as 9 diseases in open-access papers, as found by Europe PMC text mining. Sharing a sentence is not in itself a finding about the gene and the disease. The quoted sentences say what the papers report.
cyst (1 paper, 2020). A sac-like closed membranous structure that may be empty or contain fluid or amorphous material. "After generating the deletion and complementation strains for CST4, CST8, CST9, and MCP3, these parasites were assayed for parasite and cyst biology." (PMID 32019789, 2020). "IFA showed that cyst wall proteins CST4, CST8, CST9, and MCP3 were successfully knocked out and complemented back." (PMID 32019789, 2020). "Due to their cyst wall localizations, TgME49_258870, TgME49_204340, and TgME49_310790 were renamed CST7, CST8, and CST9, respectively." (PMID 32019789, 2020). "While CST4, CST8, and CST9 do not seem to play a role in determining cyst size, a lack of MCP3 resulted in statistically smaller cysts." (PMID 32019789, 2020).
lung adenocarcinoma (1 paper, 2025). A carcinoma that arises from the lung and is characterized by the presence of malignant glandular epithelial cells. "No causal relationships were found for genetically predicted cystatin 8, ‐B, ‐D, ‐F, or ‐M with squamous cell lung carcinoma, lung adenocarcinoma, and NSCLC." (PMID 40641363, 2025). "This Mendelian randomization study revealed a causal association between genetically predicted cystatin 8 and squamous cell lung carcinoma, while Cystatin D was linked to lung adenocarcinoma after outlier adjustment." (PMID 40641363, 2025). "In the two‐sample MR analysis, the IVW analysis revealed positive causal associations between genetically predicted Cystatin 8 and squamous cell lung carcinoma, and cystatin D and lung adenocarcinoma after outlier removal." (PMID 40641363, 2025).
lung carcinoma (1 paper, 2025). "Moreover, no outlier SNPs were determined in the causal relationship between cystatin 8 and lung cancer using leave‐one‐out analysis." (PMID 40641363, 2025). "Previous studies have reported higher serum Cystatin 8 concentrations in lung cancer patients compared to healthy individuals." (PMID 40641363, 2025). "Mechanistically, Cystatin 8, secreted by lung cancer cells, could degrade the endothelial glycocalyx, exposing adhesion molecules such as E‐selectin." (PMID 40641363, 2025). "Symmetry in the funnel plot suggested no heterogeneity within the causal association between Cystatin 8 and lung cancer." (PMID 40641363, 2025).
male infertility (1 paper, 2024). The inability of the male to effect fertilization of an ovum after a specified period of unprotected intercourse. "Mice lacking 8 cystatin genes (Cstl1, Cst11, Cstdc1, Cst12, Cst8, Cst13, Cst9, and Cstdc2) on chromosome 2 possess defective sperm maturation and male infertility." (PMID 38169386, 2024).
squamous cell lung carcinoma (1 paper, 2025). A carcinoma arising from squamous bronchial epithelial cells. "In conclusion, genetically predicted Cystatin 8 was causally associated with squamous cell lung carcinoma." (PMID 40641363, 2025). "The forest plot also identified causal effects between genetically predicted Cystatin 8 and squamous cell lung carcinoma." (PMID 40641363, 2025). "Genetically predicted Cystatin 8 was causally associated with squamous cell lung carcinoma (OR = 1.062, 95% CI: 1.004–1.124, p = 0.035)." (PMID 40641363, 2025). "Genetically predicted Cystatin 8 was causally associated with squamous cell lung carcinoma." (PMID 40641363, 2025). "In this study, our findings revealed a significant causal association between Cystatin 8 and squamous cell lung carcinoma risk via the IVW, weighted median, and weighted mode approaches, suggesting that Cystatin 8 may act as a potential risk factor." (PMID 40641363, 2025). "The involvement of Cystatin 8 in protease inhibition can influence cancer cell proliferation and metastasis, providing a plausible mechanistic link to its impact on squamous cell lung carcinoma." (PMID 40641363, 2025). "Causal relationship was identified between genetically predicted cystatin 8 and squamous cell lung carcinoma using IVW analysis (OR = 1.062, 95% CI: 1.004–1.124, p = 0.035)." (PMID 40641363, 2025). "Therefore, the role of Cystatin 8 in squamous cell lung carcinoma warrants further investigation to elucidate the exact biological mechanisms." (PMID 40641363, 2025).
cancer (1 paper, 2025). A tumor composed of atypical neoplastic, often pleomorphic cells that invade other tissues. "For instance, Cystatin 8 is primarily involved in reproductive biology but may also contribute to cancer pathogenesis." (PMID 40641363, 2025). "Given its potential as a therapeutic target, Cystatin 8 could pave the way for the development of novel treatments or biomarkers for this cancer subtype." (PMID 40641363, 2025).
Tumor (1 paper, 2021). "Tumor microenvironment related genes ADGRG7, CSN3, CST8, KRT81, MUC7, MYH6, and SEZ6 are valuable predictors for HNSCC patient survival." (PMID 33530209, 2021). "The role of ADGRG7 and CST8 in tumor biology has not been reported." (PMID 33530209, 2021). "Functional analysis of ADGRG7, CST8, and SEZ6 in tumor biology has not been reported." (PMID 33530209, 2021).
CST8 also shares sentences with these, for which no sentence is quoted: lysosomal storage disease (1 paper); thymoma (1).